NLRC5 (NLR family CARD domain containing 5)
Diseases named in the same sentence as NLRC5 in open-access papers (continued):
Sharing a sentence is not in itself a finding about the gene and the disease.
cancer (continued). "The increased efficiency of NLRC5-SA to upregulate MHC-I expression and to cause significant changes in MAPs strengthens the translational potential of NLRC5-SA for cancer immunotherapy." (PMID 37108368, 2023). "We further investigated the transcriptional characteristics of NLRC5+ cancer cells using the Gene Ontology pathways from GSEA, which showed overall increased expression of IFN, APM, and T-cell mediated cytotoxicity pathways." (PMID 38235131, 2023). "NLRC5 expression was found mostly in the immune compartment, specifically in T lymphocytes and natural killer (NK) cells, with few cancer cells displaying NLRC5 expression." (PMID 38235131, 2023). "An analysis of the NLRC5 gene in multiple cancer types revealed that EOC patients (n = 489) displayed the highest frequency of copy number loss at 72.2%." (PMID 38067396, 2023). "The smaller size of NLRC5-SA renders it an attractive candidate for exploring its potential to boost cancer immunogenicity via restoring the expression of MHC-I." (PMID 37108368, 2023). "Classical HLA class I haplotypes were expressed in almost all cellular components of the OC TME, but like NLRC5, there was less expression in the cancer cell population for all three HLA haplotypes." (PMID 38235131, 2023). "For instance, NLRC5 is upregulated in some tumors and has been proven to play a significant role in cancer immune surveillance through the recruitment and activation of CD8+ T-cells." (PMID 35734437, 2022). "Downregulation of the NLRC5 transcription factor is associated with decreased expression of target genes such as MHC-I, ß2M, TAP, and immunoproteasome subunits in many cancers, including prostate, lung, uterine, melanoma, and thyroid." (PMID 36142818, 2022). "Under expression of NLRC5 will cause impaired MHC class I activity, thus, increased risk for cancer and result in poor prognosis." (PMID 36268271, 2022). "The DNA methylation level of the Nlrc5 promoter varies across cancers, but it is the most methylated among MHC-I genes, and its expression is responsive to DNMTi treatment." (PMID 34681626, 2021). "IFNγ stimulates MHC-I expression in cancer through multiple ways, of which the induction of NLRC5 expression followed by the formation of CITA enhanceosome is the principal mechanism of IFNγ-induced increase in MHC-I." (PMID 34201655, 2021). "Since IFNγ strongly induces NLRC5 gene expression, further studies in normal and cancer cells are needed to resolve the conundrum of STAT1-mediated gene activation and EZH2-mediated epigenetic repression of the same target genes." (PMID 33671123, 2021). "Developing optimized reagents and methods will clarify such nuances on the predictive potential of NLRC5 expression in cancers." (PMID 33671123, 2021). "Genetic alterations of NLRC5 (copy number loss, somatic mutations and promoter methylation) dramatically reduced MHC-I expression across 16 cancer types." (PMID 34201655, 2021). "Since its discovery as the transcriptional coactivator of MHC-I and certain APM genes in 2010, NLRC5 has raised the hope of exploiting it to correct MHC-I expression defects in cancer immunity." (PMID 33671123, 2021). "The classI transactivator NLRC5 is a transcriptionalregulator of the MHC class I genes, but the promoter region of NLRC5 is frequently methylated among cancers,resulting in the reduction of MHC class I gene expression." (PMID 33465324, 2021). "EZH2-mediated histone methylation represses NLRC5 in stem cells and cancer cells, whereas IFNγ promotes the same events in macrophages on certain genes." (PMID 33671123, 2021). "Even though this elevated NLRC5 expression was thought to result from high inflammatory conditions in these cancers, studies showing NLRC5 protein expression by immunohistochemistry reveal increased staining within epithelial cells." (PMID 33671123, 2021). "The most obvious and direct application of NLRC5 to cancer immunotherapy would be to restore MHC-I expression in poorly immunogenic cancers." (PMID 33671123, 2021).
cancer (continued). "A breakthrough in understanding the regulation of MHC-I genes and their defective expression in cancers came from the work of Kobayashi group on the nucleotide-binding leucine-rich repeat-containing receptor (NLR) family protein NLRC5." (PMID 33671123, 2021). "Nonetheless, recent advances in understanding the epigenetic regulation of NLRC5 has opened alternate approaches to restore MHC-I expression in cancers." (PMID 33671123, 2021). "For instance, genetic studies have revealed that NLRC5, an HLA class I transactivator, is an important target for cancer immune evasion." (PMID 32047958, 2020). "Accumulating evidence from research presents that NLRC5 plays an important role in immune evasion of cancers, and is a therapeutic target." (PMID 33013364, 2020). "We observed a novel mechanism of genetic induction of MHC-I in cancer cells through upregulation of the MHC-I transactivator NLRC5." (PMID 32355214, 2020). "Epigenetic and (post-)transcriptional dysregulations relevant in the stabilization of NFkB, IRFs, and NLRC5 are often responsible for MHC-I downregulation in cancer." (PMID 32630675, 2020). "For instance, NLRC5 is known to influence cytokine response via immune pathways and is suggested as a novel biomarker for cancer patient prognosis and survival." (PMID 32397189, 2020). "(Epigenetic) downregulation of NLRC5 expression has been observed as a mechanism of immune evasion in several types of cancer, including colorectal, ovarian, breast and uterine cancers." (PMID 32630675, 2020). "An important contradiction in enhancing NFkB-, IFN-, and NLRC5-mediated MHC-I expression is the dual role of these pathways in cancer." (PMID 32630675, 2020). "In in vitro T cell coculture experiments, expression of NLRC5 by Panc02SIY100 is sufficient to enhance the ability of activated 2C cells to control cancer cell growth." (PMID 32355214, 2020). "NLRC5 expression was significantly associated with the activation of CD8+ cytotoxic T cells and patient survival in multiple cancer types, the low expression of NLRC5 is correlated with the poor survival rate of cancer patients." (PMID 30453994, 2018). "Better awareness of the multiple roles of NLRC5 will help to define its overall contribution to immune responses and cancer." (PMID 28261210, 2017). "In a recently published study by Yoshihama and colleagues, our understanding of the role of NLRC5 in human cancer was greatly expanded." (PMID 27729860, 2016). "Targeting NLRC5 promoter demethylation through TRED-I system can upregulate MHC-I, B2M, TAP1 and genes encoding immune proteasome components (LMP2/PSMB9/β1i, LMP7/PSMB8/β5i), thereby enhancing CD8+T cell-mediated anti-cancer immunity." (PMID 40191187, 2025). "By elucidating these mechanisms, this study provides new insights into the interplay between IFN-γ, miR-4319, and NLRC5, which could have significant implications for improving cancer immunotherapy strategies." (PMID 40596738, 2025). "This might be useful in cancer immunotherapy since it prevents cancer cells from escaping immunosurveillance, as NLRC5 is boosted in SKBR3 BC cells by IFN-γ along with overexpression in MHC-I (HLA-ABC) expression." (PMID 40098955, 2025). "Altogether these observations add a layer of complexity to the already novel node represented by NLRC5 at the intersection between ‘non-self’, ‘deregulated-self’, and immunity and raise therefore NLRC5 to a multilevel modulator of metabolism, anti-microbial, and anti-cancer immune responses." (PMID 39035010, 2024). "Whereupon, we speculate that whether the inconsistent role of NLRC5 in different microenvironment of cancer was dependent on regulating dMMR." (PMID 38822039, 2024). "As previous work also identified somatic mutations of NLRC5 in 4.8% of EBV-positive NPCs 40, but whether these mutations affect BTN2A1 and BTN3A1 expression remains to be investigated in clinical NPC cancers." (PMID 36632221, 2023).
cancer (continued). "However, the large molecular size of NLRC5 restrains its potential immunotherapeutic utility to restore MHC-I expression in cancers." (PMID 37108368, 2023). "Defects in NLRC5 expression or function are observed in many types of human tumors, including OC, with NLRC5 being the most downregulated gene among immune-related genes in cancer." (PMID 38235131, 2023). "As NLRC5 plays key role in the activation of MHC-I expression which is commonly lost in cancer immune evasion, NLRC5 could be the point that can switch on antitumor immunity." (PMID 37508545, 2023). "NLRC5-SA upregulates MHC-I in mouse and human cancer cells as efficiently as full-length NLRC5." (PMID 37108368, 2023). "Other dMMR/MSI‐associated immune escape mutations that varied in frequency between cancer types included RPL22, which was enriched in EC, and the antigen processing and presentation pathway components B2M, NLRC5, TAP2, and HLA‐B, which were more commonly disrupted in CRC." (PMID 35262923, 2022). "As could be expected, CIITA is a major target for cancer immune escape mechanisms, and ectopic expression of CIITA and NLRC5 present promising avenues in cancer vaccination strategies." (PMID 33499042, 2021). "In this endeavor, NLRC5 could be used to facilitate direct identification of MHC-I bound peptides from cancers that display low level of MHC-I expression." (PMID 33671123, 2021). "Notably, down-regulation of NLRC5 has been observed in multiple cancer types, resulting in evasion of immune elimination." (PMID 33602823, 2021). "These discordant results may result from the antitumor immune response elicited by NLRC5 overcoming any growth stimulatory functions of NLRC5 in cancer cells." (PMID 33671123, 2021). "However, unlike small molecule drugs that can be administered orally or parenterally, NLRC5 must be directly delivered to cancer cells and efficient delivery methods need to be developed." (PMID 33671123, 2021). "An important impediment to deliver NLRC5 to cancer cells would be its large size." (PMID 33671123, 2021). "The discoveries that NLRC5 is the key transcriptional activator of MHC-I and APM genes, and genetic lesions and epigenetic modifications of NLRC5 are the most common cause of MHC-I defects in cancers, have raised the hopes for restoring MHC-I expression." (PMID 33671123, 2021). "For example, epigenetic or genetic alterations such as promoter methylation, genetic mutations, or copy number loss of NLRC5 gene can cause impaired expression or function of NLRC5, associated with reduced MHC class I expression, impaired CD8 cell recruitment, and poor survival of cancer patients." (PMID 34782627, 2021). "This limitation can be mitigated by selective expression of NLRC5 in cancer tissues." (PMID 33671123, 2021). "Delivery of NLRC5 via oncolytic viruses could be one approach that can be tested as the many OV platforms are in advanced clinical trials for cancer immunotherapy." (PMID 33671123, 2021). "Why does the predictive potential of NLRC5 expression vary in different cancers?" (PMID 33671123, 2021). "Delivery of NLRC5 to cancers may also be combined with a limited use of epigenetic modifiers to relieve repression on MHC-I and APM promoters." (PMID 33671123, 2021). "Hence, in addition to using epigenetic modifiers, other approaches should be envisioned to restore MHC-I expression in cancers showing defective NLRC5 expression." (PMID 33671123, 2021). "Interestingly, NLRC5 was repressed by H3K27me3 in MHC-I low cancers and induced following PRC2 disruption." (PMID 31564637, 2019). "This may suggest that CYLD, TRAF3 and NLRC5 aberrations are critical for oncogenesis for a major subset of these cancers." (PMID 29933636, 2018). "The authors in this study included bioinformatics-based approaches to assess the expression pattern of NLRC5/CITA and MHCI in human cancer thereby providing a much better understanding of how NLRC5/CITA expression correlates with other immune parameters in the setting of human tumors." (PMID 27729860, 2016).
cancer (continued). "Moreover, these authors used this approach to determine that expression of NLRC5/CITA correlated with survival in several cancer types including melanoma, rectal cancer, bladder cancer, uterine cancer, cervical cancer and head/neck cancer." (PMID 27729860, 2016). "Therefore, the level of NLRC5 expression in cancer is tissue-dependent." (PMID 38961101, 2024). "To test our hypothesis that NLRC5 expression in cancer cells results in better patient survival, we first probed the RNA-Seq TCGA and microarray database of human OC samples for expression of NLRC5 and its main target genes, including the classical HLA class I (HLA-A-B-C)." (PMID 38235131, 2023). "The loss of key transcription factors, such as NF-κB and NLRC5, and epigenetic alterations (such as DNA hypermethylation and downregulation of histone deacetylases) can affect the transcription of MHC-I pathway genes, thereby contributing to immune evasion of cancer cells." (PMID 36142818, 2022). "Finally, we explore the possible avenues of exploiting NLRC5 for cancer immunotherapy." (PMID 33671123, 2021). "NLRC5 plays an important role in regulation of MHC class I expression, and therefore constitutes a target for cancer immune evasion." (PMID 40596738, 2025). "Recently, these data were confirmed and extended through a genome-wide CRISPR screen demonstrating the importance of endogenous NLRC5 for the expression of BTN3A1–3, and for cancer cells’ recognition and killing by Vγ9Vδ2 T cells." (PMID 39035010, 2024). "With regard to NLRC5, we did not witness its role in the transcriptional induction of endogenous BTN2A1 and found just a weak correlation between NLRC5 and BTN2A1 transcript abundance in M. tuberculosis patients and ‘The Cancer Genome Atlas’ cancer samples." (PMID 39035010, 2024). "A recent study reported that PRC2 complex containing MTF2 represses expression of NLRC5 and its target genes, including MHC‐I and antigen presentation machinery‐related genes, in cancer cells." (PMID 37452654, 2023). "NLRC5-SA induced MHC-I expression to a level comparable to NLRC5-FL in EL4 cells and in human cancer cells." (PMID 37108368, 2023). "MHC I expression can be modulated by cancer cells through DNA hypermethylation, histone deacetylation, and the trimethylation of H3K27 on the promoters of heavy chain, B2M, APM components, and NLRC5." (PMID 38067396, 2023). "Lastly, the expression of NLRC5, a key regulator of MHC-I transcription, has been found to be correlated with MHC-I expression and patient survival in several cancer types including ovarian, breast, and colorectal cancers as a mechanism of immune evasion." (PMID 35296095, 2022). "The different expression of NLRC5, SLC7A7 and PKN1 provided valuable information for future investigation and development of novel cancer therapy." (PMID 35745070, 2022). "One study on breast cancer found that the promotion of NLRC5 that is done by INF-y which in turn will upregulate the MHC class I receptors, thus increasing the effectiveness of cancer immunotherapy." (PMID 36268271, 2022). "In fact, in the case of cancer, in which MHC class I also plays crucial roles, NLRC5 was found to be the most critical host factor targeted by cancer cells to evade anti-cancer immunity." (PMID 34782627, 2021). "As the TCGA datasets represent only bulk mRNA from cancer, stromal and immune cells, additional parameters such as immune and stromal cell signatures could be used to stratify the TCGA study cohorts and evaluate the predictive potential of NLRC5 expression in cancer subsets." (PMID 33671123, 2021). "As the NLRC5-mediated regulation of inflammation and MHC-I expression has potential application in cancer immunotherapy (discussed later), it is important to understand the underlying mechanisms regulating its expression." (PMID 33671123, 2021). "Here, we provide an overview of cancer immunity mediated by CD8+ T cells and the functions of NLRC5 in MHC-I antigen presentation pathways." (PMID 33671123, 2021).
cancer (continued). "Distinguishing the impact of NLRC5-driven MHC-Ib expression from that of MHC-Ia expression and their contribution to cancer immune surveillance in human tissues will be very challenging." (PMID 33671123, 2021). "NLRC5/CITA was known to be an important regulator of MHCI molecules, yet until recently, its role in the setting of human cancer was poorly defined." (PMID 27729860, 2016). "In SK-BR-3 BC cells, IFN-γ promotes NLRC5 with overexpression of HLA-ABC, which may help prevent cancer evasion from immunosurveillance and aid in cancer immunotherapy." (PMID 40098955, 2025). "Additionally, recent publications examined the role of NLRC5 and MHC-I molecules in cancer immunotherapy sensitivity." (PMID 38915093, 2024). "Given the role of NLRC5 in cancer immune evasion, the efficacy of immunotherapy may be relatively poor for HCC patients with high expression of NLRC5." (PMID 39132868, 2024). "Compared with immune evasion, these may suggest that NLRC5 and MHC-I reduction may facilitate the formation of a global dedifferentiation phenotype in cancer cells, which suggests the progression of cancer growth and the initiation of cancer cell communities." (PMID 37508545, 2023). "The discovery of NLRC5 as the key transcriptional activator of MHC-I and APM genes that undergoes similar genetic and epigenetic repression in cancers has raised the possibility of using NLRC5 directly to restore MHC-I expression without causing undesirable side effects." (PMID 37108368, 2023). "NLRC5 is a major regulator of the expression of the MHC-I gene complex, including HLA-A, HLA-B, HLA-C, β2m, LMP2, LMP7 and TAP1, which are necessary for the presentation of neoantigens to CD8+ T cells resulting in the elimination of cancer cells." (PMID 34681626, 2021). "In addition, recurrent breakpoints of SVs targeting cancer genes commonly occurred in frequently deleted regions, e.g., CDKN2A on 9p21.3, MAML2 and ATM on 11q21-22, RAD51B, and TRAF3 on 14q 24-32.3, CYLD and NLRC5 on 16q12.1-13." (PMID 34234122, 2021). "The ability of NLRC5 to promote cancer immunogenicity by upregulating MHC-I and APM may also contribute to cancer immune surveillance." (PMID 33671123, 2021). "Provided that NLRC5 and its target genes are devoid of irreversible genetic defects, treatment with type I IFN should therefore represent a way of raising the levels of NLRC5 and the immunogenicity of cancer cells." (PMID 27437103, 2016). "In healthy cells and cancer cells with soft defects, APM and MHC I genes can be induced by the IFN regulatory factor 1 (IRF-1), NF-κB, and the NOD-like receptor family caspase recruitment domain-containing 5 (NLRC5) in response to stimulatory cytokines such as TNF-α and IFN-γ." (PMID 38067396, 2023). "To gather information about p300 and CBP in human cancer, we examined The Cancer Genome Atlas (TCGA) dataset and found significant correlations between EP300 or CBP mRNAs and genes identified by our integrative RNA-seq and ATAC-seq analyses, including RELA, STAT1, NFKB1, IFNGR2, and NLRC5." (PMID 33602823, 2021). "Hence, it appears that the downregulation of NLRC5 and MHC-I in cancer cells could be a part of the global genetic de-differentiation program that accompanies progressive cancer growth in order to maintain the cancer initiating cell population rather than an immune escape program." (PMID 33671123, 2021).